NSUN2 (NOP2/Sun RNA methyltransferase 2)
Diseases named in the same sentence as NSUN2 in open-access papers (continued):
Sharing a sentence is not in itself a finding about the gene and the disease.
tumor (continued). "The results identify NSUN2 as a critical glucose sensor that drives tumor-immune glucose metabolic reprogramming through m5C modification." (PMID 40765828, 2025). "In genetically engineered mouse models, NSUN2 deletion significantly curtails tumor growth and improves survival upon chemotherapy and tyrosine kinase inhibitor treatment." (PMID 40083919, 2025). "Conversely, NSUN2 overexpression accelerates in vivo tumor growth, resulting in increased tumor volume and weight." (PMID 40114967, 2025). "In summary, NSUN2 plays a central role in chemotherapeutic and targeted therapy resistance across multiple tumor types through diverse m5C-dependent and microenvironment-mediated mechanisms." (PMID 41256859, 2025). "Tumor-derived lactate facilitates N-alpha-acetyltransferase 10 (NAA10)-mediated K508 lactylation of NSUN2, increasing its catalytic activity." (PMID 40859309, 2025). "Western blot analysis of five normal and five tumor tissues revealed elevated NSUN2 protein levels in NPC tissues." (PMID 41463199, 2025). "A previous study revealed that NSUN2 is highly expressed in a variety of tumours, and is related to the occurrence and development of tumours." (PMID 39924557, 2025). "SREBP2 and NSUN2 expression levels exhibited significant positive correlations with TTPAL tumor expression." (PMID 40713894, 2025). "When combined with PD-1 therapy, Nsun2-i4 further amplifies tumor growth inhibition compared to monotherapy." (PMID 40114967, 2025). "Functional assays show that NSUN2 knockdown enhances tumor sensitivity to cisplatin, increases DNA damage levels, and impairs homologous recombination repair due to reduced MRE11 recruitment." (PMID 41256859, 2025). "NSUN2 has recently attracted considerable attention due to its crucial role in driving tumor development in an m5C-dependent manner." (PMID 41462962, 2025). "Through these functions, NSUN2 plays a pivotal role in cell growth, survival, and environmental adaptation, laying a molecular foundation for its involvement in tumor development and immune regulation." (PMID 41256859, 2025). "Then we co-cultured CD8+ T cells with malignant cells and found that restricting glucose uptake by malignant cells or silencing NSUN2 effectively alleviated tumor-driven metabolic suppression in CD8+ T cells." (PMID 40765828, 2025). "NSUN2 plays a critical role in tumor initiation and proliferation, primarily through gene expression regulation mediated by RNA m5C modification." (PMID 41256859, 2025). "We found that higher expression of NSUN2 was correlated with the presence of pathological satellites (P = 0.025), larger tumour size (P = 0.013) and microvascular invasion (P = 0.041)." (PMID 39924557, 2025). "Knockout of NSUN2 was shown to suppress tumor formation, proliferation, and metastasis while increasing chemosensitivity and disrupting the c-Myc-NSUN2 feedback loop in ATC." (PMID 40819127, 2025). "Looking ahead, systematic dissection of NSUN2’s role across different tumor TMEs—particularly its regulation of immune cell infiltration and metabolism—will elucidate its dynamic contribution to tumor-immune co-evolution." (PMID 41256859, 2025). "Knocking out NSUN2 rendered tumors more sensitive to cisplatin, reducing tumor growth and increasing DNA damage levels, which was associated with reduced MRE11 recruitment to damage sites, impairing homologous recombination repair." (PMID 41462962, 2025). "As early as 2006, NSUN2 was found to methylate RNA polymerase III transcripts in tumor cells, mediating Myc-induced cell proliferation and growth; The active nucleophile Cys321 catalyzes m5C methylation, with Cys271 serving as the release site." (PMID 41413017, 2025). "NSUN2 is highly expressed in NSCLC tumor tissues, and the elevated expression level is closely related to tumor grading and size, accompanied by poor prognosis in patients with NSCLC." (PMID 41462962, 2025).
tumor (continued). "Recently, several small‐molecule inhibitors targeting the m5C methyltransferase NSUN2 have been identified, showing promising anti‐tumour effects." (PMID 40088428, 2025). "Collectively, NSUN2 regulates the tumor immune microenvironment and promotes immune escape in various cancers through multiple molecular axes, including PD-L1, YBX1, ALYREF, and the SNHG15/miR-545-3p pathway." (PMID 41256859, 2025). "By profiling tumor NSUN2 expression and m5C modification landscapes, patients suitable for combined NSUN2 inhibition and ICI therapy can be selected, enabling precision immunotherapy." (PMID 41256859, 2025). "NSUN2-mediated metabolic regulation also affects the tumor microenvironment and immune cell function, supporting immune evasion." (PMID 41256859, 2025). "Specifically, NSUN2 stabilizes the mRNAs of various oncogenes via m5C modification, thereby enhancing their post-transcriptional expression and promoting tumor cell proliferation." (PMID 41256859, 2025). "The study reveals that NSUN2 is significantly upregulated in ATC and is associated with tumor dedifferentiation and poor prognosis." (PMID 40463874, 2025). "NSUN2 overexpression markedly promotes HCC cell proliferation and metastasis, while NSUN2 knockdown inhibits tumor growth and invasion." (PMID 41256859, 2025). "Given the high genomic instability typically observed in tumor cells, NSUN2 enhances the tolerance of tumor cells to DNA damage by regulating the expression of repair-related genes, ensuring their sustained proliferative capacity." (PMID 41256859, 2025). "Additional researches indicate that knockdown of METTL14, NAT10, and NSUN2 in OS cell lines significantly inhibits tumor growth in nude mice 11-13." (PMID 39897026, 2025). "Consistently, in vivo, NSUN2 overexpression or additional glucose supplementation significantly enhances tumor growth." (PMID 40765828, 2025). "Several kinds of mRNAs were highly expressed in tumor-surrounding tissues, among which NSUN2 was the most significantly elevated." (PMID 41354740, 2025). "NSUN2 also promotes cell migration, invasion, and metastasis, and in vivo studies show that NSUN2 enhances tumor growth and metastasis to the liver, lungs, intestines, and ascites formation." (PMID 40114967, 2025). "Exosomes derived from DLBCL cells transfer NSUN2 to other tumor cells, promoting proliferatio, M2 macrophage polarization, immune evasion, and inhibiting apoptosis." (PMID 41346602, 2025). "NSUN2 expression, along with several clinicopathological indicators, such as pathological satellites, larger tumour size and the presence of microvascular invasion, are important prognostic factors for predicting the OS rate and RFS rate of HCC patients." (PMID 39924557, 2025). "Inhibitors of m5C methyltransferases, such as NSUN2 inhibitors, have been shown to significantly reduce tumor growth and metastasis while enhancing the sensitivity of cancer cells to chemotherapeutic agents like cisplatin and 5-fluorouracil." (PMID 40114967, 2025). "The western blotting results further revealed that NSUN2 expression levels were significantly higher in tumor samples than normal samples." (PMID 41436732, 2025). "In the U87 human glioma cell line, NSUN2 regulates tumor cell migration by modulating the autocrine chemokine (ATX)-lysophosphatidic acid (LPA) axis." (PMID 40370440, 2025). "Tumour growth in the NSUN2‐overexpression group of mice was significantly greater than that in the control group." (PMID 40156167, 2025). "As an m5C methyltransferase, NSUN2 can modify oncogenes or DNA repair-related gene RNAs to enhance tumor cell tolerance to chemotherapeutic agents such as cisplatin or paclitaxel." (PMID 41256859, 2025). "Upregulation of the m5C writer NSUN2 and the ac4C writer NAT10 is implicated in tumor progression through the regulation of cellular metabolic mechanisms." (PMID 39897026, 2025). "In gastrointestinal malignancies, NSUN2 typically promotes tumor progression through multiple pathways." (PMID 41462962, 2025).
tumor (continued). "m6A, driven by METTL3, modulates key oncogenic and tumor-suppressor pathways, while m5C, mediated by NSUN2, supports codon-dependent translation for cancer progression." (PMID 40463874, 2025). "Specifically, NSUN2-mediated m5C modification stabilizes oncogene mRNA, facilitating tumor progression." (PMID 40114967, 2025). "The NSUN2-mediated GLUT1 stabilization enhances the competitive advantage of tumor cells in glucose acquisition, creating a positive feedback loop that accelerates malignancy and exacerbates CD8+ T cell dysfunction." (PMID 40765828, 2025). "In HCC, NSUN2 contributes to tumor progression by up-regulating PKM2 and stabilizing its mRNA, thereby promoting glycolysis and offering potential therapeutic avenues for HCC patients." (PMID 41256854, 2025). "Functional studies have demonstrated that NSUN2 promotes leukemia cell proliferation, enhances tumor growth in xenograft models, and confers cell resistance to ferroptosis." (PMID 41462962, 2025). "Functional assays demonstrate that NSUN2 knockdown inhibits cancer cell proliferation, migration, and invasion, and reduces tumor formation and lymph node metastasis in vivo." (PMID 41256859, 2025). "This proliferative mechanism is also observed in retinoblastoma, where NSUN2 accelerates tumor growth by up-regulating the purine synthesis-related protein PFAS." (PMID 41446042, 2025). "The average tumor volume of the harvested tumors from the NSUN2 overexpressed group was larger than that from the NC group." (PMID 38403250, 2024). "The average tumor weights for the NC and NSUN2 overexpression groups were 0.239 g and 0.050 g, respectively." (PMID 38403250, 2024). "The results indicated that high levels of NSUN2 expression were positively correlated with NSCLC tumor grade and size." (PMID 38403250, 2024). "The results showed that NSUN2 knockdown inhibited tumour growth and decreased tumour weight and Ki67 expression levels, while SKIL overexpression rescued these effects." (PMID 38468490, 2024). "It has been reported that tRNA m5C has a significant impact on the survival of tumor-initiating cells, as well as on tumor development and metastasis, and this effect is induced by Nsun2 knockout." (PMID 39340806, 2024). "The genetically engineered mouse orthotopic CRC model also indicated that the NSUN2 heterozygotes exhibited significantly less tumor burden in AOM/DSS‐induced CRC than the control." (PMID 38769664, 2024). "In CRC tumour tissues, the protein expression levels of NSUN2 and SKIL showed a significant positive correlation." (PMID 38468490, 2024). "In tumor cells, glucose acts as a cofactor for NSUN2 and binds to its amino acid 1-28 region to promote oligomerization and activation of NSUN2." (PMID 39867908, 2024). "In line with the results from the TCGA and GEO cohorts, high NSUN2 protein expression was more frequently observed in NSCLC tumor tissues than in normal tissues." (PMID 38403250, 2024). "Western blot results similarly demonstrated a significant elevation of NSUN2 expression levels in tumor samples compared to normal samples, and in HNSCC cells compared to HOK cells." (PMID 39595099, 2024). "Mechanistically, NSUN2 promotes tumor development mainly through the methylation of related mRNAs and lncRNAs." (PMID 39340806, 2024). "NSUN2 and ALYREF serve as independent risk factors for both overall survival and disease-free survival, and are linked to tumor staging and distant metastasis." (PMID 39695216, 2024). "Results indicated that tumours with high NSUN2 expression are more sensitive to verteporfin treatment, hinting at its potential therapeutic effects in CRC." (PMID 38468490, 2024). "In summary, our data conclusively demonstrated that tumor‐derived lactic acid facilitates the direct lactylation of NSUN2, enhancing its RNA‐binding capacity and thereby contributing to the m5C‐mediated progression and metastasis of CRC." (PMID 38769664, 2024).
tumor (continued). "We found elevated NSUN2 expression levels strongly correlate with tumor grade and size, predicting poor outcomes for NSCLC patients." (PMID 38403250, 2024). "Both in vitro and vivo studies were performed to evaluate the impact of NSUN2 manipulation on tumor growth and metastasis." (PMID 39595099, 2024). "Our results showed that NSUN2, DNMT1, DNMT3A, DNMT3B, TRDMT, and ALYREF were related to high or low tumor risk, while NOP2 was related to the pTNM stage of tumors." (PMID 38579085, 2024). "M5C, in conjunction with its regulators such as NSUN2, plays a significant role in the initiation and growth of various tumour; hence, it is a potential therapeutic target for disease intervention." (PMID 38572667, 2024). "Following this, the impact of ectopic expression of LAMC2 in NSUN2-depleted HNSCC cells was assessed by using a xenograft tumor model." (PMID 39595099, 2024). "An increasing body of evidence suggests that NSUN2 participates in the promotion of certain neoplasms, including non-small cell lung cancer, bladder cancer, prostate cancer, esophageal cancer, and HNSCC." (PMID 39595099, 2024). "For example, the expression of NSUN2 was positively related to that of ICP genes in LIHC, OV, KIRC and BRCA, but negatively associated with that of ICPs genes in a few tumor types, such as LUSC." (PMID 37769000, 2023). "Conclusively, this study initially demonstrated that NSUN2 is necessary for oncogenic gene activation in RB, expanding the current understanding of dynamic m5C function during tumour progression." (PMID 37228185, 2023). "Among the regulators of m5C modification, NSUN2 is an important methyltransferase; however, NSUN2 is less studied in the context of tumor, and its functions in immunology are largely unclear." (PMID 37769000, 2023). "Previous studies have shown that NSUN2 is involved in the regulation of m5C modification and affects tumor progression." (PMID 36183976, 2023). "NSUN2 down‐regulation suppressed tumour formation, proliferation, migration, invasion and lung metastasis in ATC." (PMID 37983928, 2023). "In the ESCC study, a novel NSUN2 methylated lncRNA NMR regulated tumor metastasis and drug resistance via NSUN2 and BPTF." (PMID 37275549, 2023). "To explore the oncogenic role of NSUN2 in vivo, we conducted subcutaneous tumor formation experiments." (PMID 36632452, 2023). "NSUN2 expression was positively related to the levels of neutrophils in different tumor types (except LUSC), according to the TIMER, XCELL, CIBERSORT, QUANTISEQ, CIBERSORT-ABS and MCPCOUNTER algorithms." (PMID 37769000, 2023). "In this study, we demonstrated that NSUN2‐mediated m5C RNA methylation was tumour‐specifically elevated, which fuels purine biosynthesis during the oncogenic progression of RB." (PMID 37228185, 2023). "Conclusively, we initially demonstrated that NSUN2 is necessary for oncogenic gene activation in RB, expanding the current understanding of dynamic m5C function during tumour progression." (PMID 37228185, 2023). "Further studies found that the tumor suppressor gene P57, as a downstream target of NSUN2, affected the proliferation ability of tumor cells." (PMID 37168511, 2023). "For example, in GC patients, YBX1 binds with FOXC2 (Forkhead box protein C2) mRNA, which is m5C-modulated by NSUN2, to enhance its tumor-promoting ability." (PMID 37325635, 2023). "The correlation between NSUN2 expression and clinicopathological stage in different tumor types was depicted by using the UALCAN database." (PMID 37769000, 2023). "In the present study, we found that NSUN2 also serves as an important oncogenic promoter in RB, expanding the current understanding of dynamic m5C function during tumour progression." (PMID 37228185, 2023). "The results revealed that the mRNA and protein expression levels of NSUN2 are increased in multiple tumor types." (PMID 37769000, 2023).
tumor (continued). "In line with in vitro results, NSUN2 knockdown resulted in a lower rate of tumor formation and reduced tumor burden in subcutaneous xenograft models of gefitinib-resistant H1650 and H1975 cells." (PMID 37161388, 2023). "NSUN2 was highly overexpressed in multiple tumor types either through amplification or DNA hypomethylation." (PMID 37612540, 2023). "IHC staining indicated reduced Ki67 staining in tumours from shN‐1 and shN‐2 groups, confirming that NSUN2 inhibition reduced ATC proliferation in vivo." (PMID 37983928, 2023). "Overexpression of NSUN2 resulted in gefitinib resistance and tumor recurrence, while genetic inhibition of NSUN2 led to tumor regression and overcame intrinsic resistance to gefitinib in vitro and in vivo." (PMID 37161388, 2023). "Our study unveils a novel m5C dependent cross-regulation between nuclear reader ALYREF and m5C writer NSUN2 in activation of hypermethylated m5C oncogenic RNA, which consequently leads to tumor progression." (PMID 36806253, 2023). "NSUN2 also modulates the Ras signaling pathway as well as the cell cycle, thus allowing for tumor escape from chemotherapy." (PMID 37325635, 2023). "NSUN2 has been reported to be involved in various tumor-related cell processes, including affecting proliferation, apoptosis, and sorafenib sensitivity in HCC cells." (PMID 36183976, 2023). "To further determine the impact of NSUN2 on tumor growth in vivo, we established a subcutaneous xenograft model." (PMID 37393317, 2023). "Overexpression of NSUN2 promotes proliferation and migration of tumor cells and knocking down NSUN2 inhibits these processes." (PMID 37168511, 2023). "We found that NSUN2 expression was positively correlated with the expression of RNA modification-related genes in most tumor types." (PMID 37769000, 2023). "Consistent with previous results, the acquired data revealed that NSUN2 expression was elevated in ATC samples compared to matched para‐tumour tissues." (PMID 37983928, 2023). "The data showed that the mRNA level of NSUN2 was greatly upregulated in 18 of 33 tumor types compared with paired adjacent normal tissues." (PMID 37769000, 2023). "Among these two cohorts, we found that the expression of ALYREF and NSUN2 were significantly upregulated in UCB tumor tissues compared to adjacent normal tissues." (PMID 36806253, 2023). "The results showed that NSUN2 was differentially expressed in six immune subtypes (C1, C2, C3, C4, C5, C6) of the same tumor." (PMID 37769000, 2023). "In HCC, NSUN2 mediates the m5C modification of a tumor-related lncRNA H19, increasing its stability." (PMID 37612540, 2023). "To assess their in vivo tumour formation ability, we injected NSUN2‐silenced and control Y79 cells into the eyeballs of nude mice and monitored tumour growth in orthotopic xenograft models." (PMID 37228185, 2023). "In summary, NSUN2 was highly expressed in most tumor types and correlated with poor prognosis and immune infiltration." (PMID 37769000, 2023). "CCK8 assay, EDU assay, and scratching assay showed that NSUN2 contributed to the proliferation and migration of tumor cells." (PMID 35978830, 2022). "Haematoxylin‐eosin (HE) staining and IHC were implemented to detect the expression levels of NSUN2, AR and AR‐V7 using tumour tissues harvested from xenograft model mice." (PMID 36169095, 2022). "Meanwhile, 4 out of 6 patient samples exhibited higher expression of NSUN2 protein in tumor tissues than their paired adjacent normal tissues as examined by Western blot." (PMID 35280737, 2022). "In summary, we found that NSUN2 was highly expressed in NPC tissues and the level of NSUN2 was closely correlated with tumor stage and distant metastasis." (PMID 35574373, 2022). "NSUN2 high expression implies poor clinical features, and the NSUN family is significantly associated with tumor stromal score and immune score." (PMID 35978830, 2022). "NSUN2 mRNA expression levels were significantly higher in 497 tumour samples than in 52 normal tissues (p < .01)." (PMID 36169095, 2022).